FABP3 (fatty acid binding protein 3)
Diseases named in the same sentence as FABP3 in open-access papers (continued):
Sharing a sentence is not in itself a finding about the gene and the disease.
fibrosarcoma (1 paper, 2024). A malignant mesenchymal fibroblastic neoplasm affecting the soft tissue and bone. "Hypoxia induces HIF1α expression in HT-1080 fibrosarcoma cells, leading to increased transcription of fatty acid binding proteins 3 (FABP3) and 7 (FABP7), enhancing lipid uptake and storage, which inhibits ferroptosis." (PMID 39737174, 2024).
hepatocellular carcinoma (1 paper, 2022). A malignant tumor that arises from hepatocytes. "For example, FABP2 is highly expressed in gastric cancer, whereas high FABP3 expression has been associated with poor prognosis in patients with hepatocellular carcinoma (HCC) and esophageal cancer." (PMID 35783014, 2022).
hippocampal atrophy (1 paper, 2025). "The synaptic latent factor was composed of neurogranin, FABP3, and ferritin, and showed robust associations with hippocampal atrophy in both longitudinal and mediation models." (PMID 41442069, 2025). "When tested individually, neither ferritin nor neurogranin was significantly associated with hippocampal atrophy, whereas FABP3 showed a significant interaction effect." (PMID 41442069, 2025).
liver fibrosis (1 paper, 2019). "Among the seven potential biomarkers FABP3, GALNT5, GPR84, ITGB6, MYEOV, PLEKHS1, and STRA6, we are particularly interested in GPR84 and STRA6 because they link to liver fibrosis that is a major risk factor in HCC and an independent risk factor of recurrence after hepatectomy." (PMID 31828095, 2019).
lung carcinoma (1 paper, 2024). "The in vitro experiments were performed with brain metastasis tissue sections from a patient with lung cancer that we have detected to express the target FABP3." (PMID 38393497, 2024). "Autoradiography revealed heterogeneous and high focal [18F]FNA-S-ACooP binding in brain metastasis tissue sections from a patient with lung cancer, and the radioactivity binding mainly co-localized with the anti-FABP3 positivity detected in immunofluorescence staining of adjacent tissue sections." (PMID 38393497, 2024).
lymphoma (1 paper, 2008). A malignant (clonal) proliferation of B- lymphocytes or T- lymphocytes which involves the lymph nodes, bone marrow and/or extranodal sites. "From the repressed list of genes 4 out of 9 probes had low expression in more than 95% of the human lymphomas, whose gene names include LIFR, FABP3 and EDG1/HEXIM1 (p = 0.03)." (PMID 18535662, 2008).
malignant thyroid tumors (1 paper, 2025). "As a fatty acid transporter, FABP3 hypomethylation and consequently overexpression could enhance intracellular lipid flux and activate PPARγ/RXRα signaling, which is implicated in tumor proliferation of thyroid cancer." (PMID 41019337, 2025). "The present study is among the largest studies on differential diagnosis of TC and BTN with a total of 890 samples, which suggests hypomethylation of the FABP3 gene might be biomarkers to differentiate benign and malignant thyroid tumors." (PMID 41019337, 2025).
metastatic tumors (1 paper, 2015). "Two proteins more abundant in metastatic tumors in the 2D DIGE data were also significantly elevated only in metastatic tumors in the present study, namely FABP3 and beta-hexosaminidase." (PMID 26305875, 2015).
muscular dystrophy (1 paper, 2025). Muscular dystrophy (MD) refers to a group of more than 30 genetic diseases characterized by progressive weakness and degeneration of the skeletal muscles that control movement. "FABP3 and CKM are secreted by muscle fibers into the blood upon muscle damage, particularly in cases of muscular dystrophy." (PMID 41104521, 2025).
oral cancer (1 paper, 2022). "The expression levels of FABP3, PPARG, PLIN5, ACACB, and PDK4 in oral cancer samples were significantly lower than those in adjacent normal samples (all p < 0.05) and then were included in the prognosis analysis." (PMID 36478991, 2022).
osteosarcoma (1 paper, 2025). A usually aggressive malignant bone-forming mesenchymal neoplasm, predominantly affecting adolescents and young adults. "CERS1, FABP3 and NPDC1 significantly propelled predictions towards high mitophagy, indicating these genes positively regulate mitophagy in osteosarcoma." (PMID 39834330, 2025). "Gene expression comparisons between groups corroborated these findings, demonstrating significantly higher expressions of CERS1, FABP3 and NPDC1 in high‐mitophagy osteosarcoma, whereas PLEKHF1 and LILRA2 were significantly less expressed." (PMID 39834330, 2025).
post-traumatic stress disorder (1 paper, 2021). An anxiety disorder precipitated by an experience of intense fear or horror while exposed to a traumatic (especially life-threatening) event. "In addition, FABP3−/− mice exhibit cognitive dysfunction, hyperlocomotion, and impairment of fear extinction, which demonstrates that FABP3−/− mice exhibit post-traumatic stress disorder (PTSD)-like behaviors." (PMID 33804804, 2021).
prostate tumor (1 paper, 2020). "Therefore, we found FABP3 and SERPINB2 as common genes in our treated samples and primary prostate tumor in dogs, with increase of FABP3 in all our comparative samples, but interestingly SERPINB2 was downregulated only in PC2, which was resistant to TP." (PMID 33324695, 2020).
rheumatoid arthritis (1 paper, 2021). A chronic, systemic autoimmune disorder characterized by inflammation in the synovial membranes and articular surfaces. "FABP3 was significantly correlated with “CHDI_correlations from replication data_causal network (positive correlations)”, “rheumatoid arthritis (general schema)”, and “immune response_immunological synapse formation” in the development of CRC." (PMID 34680577, 2021).
thyroid nodule (1 paper, 2025). A small circumscribed mass in the THYROID GLAND that can be of neoplastic growth or non-neoplastic abnormality. "Our study suggested that altered FABP3 methylation in tissue samples as a potential biomarker to distinguish malignant and benign thyroid nodules, and might be helpful for the pathological classification of TC." (PMID 41019337, 2025).
ventricular septal defect (1 paper, 2013). The presence of a defect (opening) in the septum that separates the two ventricles of the heart. "We have previously reported that FABP3 is highly expressed in patients with ventricular-septal defects, when compared with normal controls." (PMID 23823803, 2013). "Earlier, our group also established that FABP3 is upregulated in patients with ventricular-septal defects in comparison to normal controls, by using subtractive hybridization." (PMID 23823803, 2013).
viral myocarditis (1 paper, 2021). Myocarditis that is caused by an infection with a viral agent. "Subsequently, we learned intermolecular interactions of herbal components and their targeting heart-tissue-specific CHRM2, FABP3, TNNC1, TNNI3, TNNT2, and SCN5A and cardiac-myocytes-specific IL6, MMP1, and PLAT coupled with viral myocarditis." (PMID 34456633, 2021).
tumor (51 papers, 2007 to 2025). "The association between FABP3 hypomethylation and TC was enhanced in women, in patients with younger age, with larger tumor size and with lower FT3." (PMID 41019337, 2025). "For example, in a study involving 1331 patients with breast cancer, 94.3% of tumor samples were FABP3-positive, and this was associated with better 10-year survival rate." (PMID 38393497, 2024). "In human non-small cell lung cancer (NSCLC) tissue, increased expression of FABP3 was associated with advanced tumor metastasis and shorter overall survival." (PMID 37207357, 2023). "In recent clinical studies, FABP3 has been linked to tumor growth, but its functions have been contradictory." (PMID 36478991, 2022). "In this study we assessed in vivo, the effect of decreasing lipid uptake via FABP3 inhibition by administering a pharmacological inhibitor intracranially into tumor-bearing mice." (PMID 40661379, 2025). "In accordance with a role of LD formation in tumor development, FABP3 or FABP7‐knockout U87 cells subcutaneously xenografted show a delay in tumor growth initiation, decreased proliferation and decreased lipid staining." (PMID 38105543, 2025). "Treatment with oleanolic acid (OA) downregulates FABP3, sensitises resistant cells to sorafenib both in vitro and in vivo, and suppresses tumour growth and invasiveness." (PMID 41149452, 2025). "Immunohistochemistry revealed a strong expression of FABP3 in tumor cells, located in proximity to ABCG1+ cells." (PMID 40661379, 2025). "For example, the ferroptosis of LUAD cells will be desensitized by the upregulation of FABP3 and then the downregulation of AA in a FABP3-dependent manner due to the upregulation of circRNA_101093 via exosomes secreted by tumor cells." (PMID 38075205, 2024). "This work is to develop methods for radiolabeling of ACooP with fluorine-18 (18F) for positron emission tomography (PET) applications, and evaluate the binding of the radiolabeled ACooP in human tumor tissue sections with high FABP3 expression." (PMID 38393497, 2024). "Nevertheless, patients with high FABP3 protein expression in both breast tumor tissues and the tumor adipose microenvironment had worse prognosis." (PMID 37207357, 2023). "It was found that fatty acid binding protein 3 (FABP3) regulates mitochondrial metabolism to promote tumor progression." (PMID 37036489, 2023). "We found that the mRNA expression levels of FABP3 or FABP4 were related to different tumor stages of CRC." (PMID 34680577, 2021). "Recent clinical studies have indicated the participation of FABP3 in tumor progression with conflicting functions." (PMID 27323829, 2016). "FABP3 plays a crucial role in the occurrence and development of various cancers, through mechanisms involving mitochondrial function, lipid metabolism, and tumor immune regulation." (PMID 40717587, 2025). "In addition, we observed a correlation between five FABP3 CpG sites methylation and tumor size (CpG_7/cg18368411, CpG_8, and CpG_9.10.11, all the P values ≤ 0.016)." (PMID 41019337, 2025). "When examining the level of FABP3 expression in embryonic tumor cells, breast cancer cells, and FABP4 in breast, ovarian, prostate, bladder or liver cancer cells, low levels of both proteins were observed, which was associated with a worse prognosis in terms of overall survival." (PMID 32850012, 2020). "However, the increased FABP3 expression in tumors of the stomach, brain, small- and non-small-cell lung cancer seems paradoxical; it has been shown to increase tumor aggressiveness and poorer patient prognosis." (PMID 32850012, 2020). "Moreover, inhibition of lipid storage by FABP3 or FABP7 knockdown decreased tumor cell survival under hypoxia-reoxygenation and impaired tumorigenesis in vivo." (PMID 31835444, 2019). "However, the role of FABP3 in tumor is controversial: FABP3 can act as either a tumor suppressor or an oncogene depending on tumor types." (PMID 27323829, 2016).
tumor (continued). "Furthermore, NGS analysis revealed that NF-κB/RELA targets including CCL2, CXCL8, EDN1, IL-1β, IL-6, and SERPINE1 were further reduced and several potential tumor suppressors, such as FABP3, FADS2, FDFT1, SEMA6A, and PCK2, were synergistically induced by the Gefitinib-+IKK16 treatment." (PMID 36358633, 2022). "Furthermore, in vitro inhibition of FABP3 inhibits cell proliferation and impairs tumor growth." (PMID 33208770, 2020). "Furthermore, high expression of FABP3 or FABP4 in NSCLC was significantly associated with advanced tumor node metastasis (TNM) stage and had a negative impact on the overall survival of NSCLC patients." (PMID 27323829, 2016). "The 11 identified subtypes (FABP1-FABP12; FABP11 is identical to FABP3) exhibit tissue-specific expression and influence tumor progression through metabolic reprogramming, immune microenvironment modulation, and therapy resistance." (PMID 40717587, 2025). "In tumours, both AMɸ and AIMɸ upregulated genes involved in cholesterol and lipid transport and metabolism (such as ABCA1, APOC1, APOE, FABP3 and FABP5) compared to the background tissue." (PMID 38782901, 2024). "Autoradiography revealed heterogeneous and high focal [18F]FNA-S-ACooP binding, which mainly co-localized with the anti-FABP3 positivity.H&E and anti-CD31 staining confirmed presence of viable tumor tissue." (PMID 38393497, 2024). "MDGI/FABP3 was found overexpressed in aggressive mesenchymal GBM and the tumor vasculature, which correlated with poor patient survival." (PMID 31679081, 2020). "Among the MNA tumors (n=10), five tumor suppressor genes (among other genes) were underexpressed within the distal 1p: CAMTA1, KIF1B, PRDM2, FABP3, and CDKN2C; whereas MYCNOS and MYCN were the two top differentially upregulated genes on 2p." (PMID 23656755, 2013). "In addition, natural compounds, such as oleanolic acid and pterostilbene, have also been shown to modulate FABP3- and FABP5-related oncogenic pathways, restoring drug sensitivity and suppressing tumour cell migration, respectively." (PMID 41149452, 2025). "Notably, AKR1B1, CD36, ABCA1, PRKD1, OSBPL1A, and FABP3 showed varied expressions in specific cells, suggesting their significant roles in STAD carcinogenesis, further confirmed by elevated mRNA levels in tumor tissues via qRT-PCR." (PMID 38440405, 2024). "By comparing tumor with adjacent tissue, or comparing a metastatic tumor with non-metastatic tumor, we observed that FABP3 and 4 were expressed in a fraction of myeloid cells, and FABP4 displayed a marginal reduction in cells from metastatic tumor tissues." (PMID 35269427, 2022). "Our finding of the positive correlation between FABP3 and FABP4 expression suggest that these two proteins may act in the same signaling pathway in promoting tumor progression." (PMID 27323829, 2016). "FABP3 enhances the degradation of GPX4, a key protein in the ferroptosis resistance pathway, by promoting the generation of arachidonic acid metabolites (such as lipoxins), thereby enhancing the resistance of tumor cells to oxidative stress-induced programmed death." (PMID 40717587, 2025). "Overall, FABP3 participation in tumor progression is uncertain mainly due to the fact that FABP3 may be expressed in tumor tissue as well as in nontumor tissue such as immune cells and stromal cells, and its role may be context specific in malignant progression." (PMID 37207357, 2023).
cancer (27 papers, 2011 to 2025). A tumor composed of atypical neoplastic, often pleomorphic cells that invade other tissues. "Abnormal expression of FABP3 is associated with poor prognosis in various cancers, suggesting its potential as a biomarker for cancer diagnosis and prognosis assessment." (PMID 40717587, 2025). "All myokines identified in our study as potentially associated with cancer cachexia are normally released by various cells, predominantly within the immune system (IL-6, IL−8, FABP3) and adipose tissue (leptin, FSTL-1)." (PMID 39411315, 2024). "The lower expression of FABP3 in post-ovulatory OF compared to pre-ovulatory OF may also be linked to the fact that FABP3 overexpression induces apoptosis, as demonstrated in heart and embryonic cancer cells, and thus, its expression needs to be finely regulated when the embryo enters the oviduct." (PMID 34422946, 2021). "For example, some studies have commenced to evaluate the safety and therapeutic potential of FABP3 inhibitors in cancers." (PMID 40717587, 2025). "The expression level of FABP3 in cancer tissues is significantly higher than that in normal tissues and is positively correlated with TNM staging." (PMID 40717587, 2025). "It is important to note that Il1rap, Ifi44, Timd4, Fabp3, and Eno 2 have been reported as potential therapeutic targets and potential prognostic biomarkers for several cancers." (PMID 41011134, 2025). "In recent years, dysregulated expression of FABP3 and its potential mechanisms in various cancers have attracted the attention of researchers." (PMID 40717587, 2025). "This specific circRNA promotes cancer cell resistance to ferroptosis by reducing arachidonic acid (AA) levels and hindering its incorporation into the plasma membrane through the action of fatty acid-binding protein 3 (FABP3)." (PMID 40328736, 2025). "Future research exploring the molecular mechanisms of FABP3 and its potential as a therapeutic target may contribute to the development of more effective cancer diagnosis and treatment strategies." (PMID 40717587, 2025). "FABP3 plays a significant role in cancer and neurodegenerative diseases." (PMID 38393497, 2024). "Besides lipid synthesis, HIF1-α was also reported to increase the lipid levels of cancer cells through the direct upregulation of Fatty Acid Binding Protein 3 (FABP3) and FABP7, both involved in lipid uptake." (PMID 32932943, 2020). "Inhibitors targeting FABP3 may become novel strategies for cancer therapy." (PMID 40717587, 2025). "Our current study intentionally focused on the diagnostic performance of FABP3 methylation especially for early-stage cancer (stage I and II), and thus, in lack of the prognostic information while early-stage TC is often curable upon timely diagnosis and treatment." (PMID 41019337, 2025). "Another characteristic phenotype of cancer cells is the alteration of cell receptors, such as high glutamine uptake by an elevated expression of glutamine transporters and the overexpression of fatty acid-binding receptor proteins like ADRP, FABP3, and FABP7." (PMID 39772236, 2024). "In particular, coupling of energy metabolism between CAMs and cancer cells may be mediated by fatty acid binding proteins, such as FABP1 and FABP3, which were also upregulated in hypoxic CAMs." (PMID 30813438, 2019).
cardiovascular diseases (25 papers, 2012 to 2025). "Overall, our review highlights the promising role of FABP3 in early diagnosis and risk stratification of high-risk individuals for further evaluation, close follow-up, and aggressive management to reduce the significant morbidity and mortality associated with cardiovascular disorders." (PMID 36140383, 2022). "Our data showed that increased levels of FABP3 are correlated with measures indexing a beneficial metabolic profile whereas decreased levels of FABP3 are correlated with metabolic profiles increase individual’s risk for developing cardiovascular diseases (CVDs)." (PMID 23510163, 2013). "Our cohort demonstrated normal levels of FABP3 (ranging from 1.6 ng/mL to 19 ng/mL) in accordance with several cardiovascular disease studies." (PMID 37662953, 2023). "We described the roles of FABPs in cardiovascular disease and specifically highlighted FABP3′s potential utility as a biomarker for PAD." (PMID 36140383, 2022). "Our findings suggest that DNA methylation of FABP3 strongly influences MetS, and this may have important implications for cardiovascular disease." (PMID 23510163, 2013).
metabolic disease (12 papers, 2012 to 2025). A congenital disorder (due to inherited enzyme abnormality) or acquired (due to failure of a metabolically important organ) disorder resulting from an abnormal metabolic process. "Fatty acid-binding protein 3 (FABP3) is an intracellular FA carrier, which has been evaluated as a biomarker of atrial maladaptive remodeling in patients with metabolic disease." (PMID 34778401, 2021). "FABP3 plays a significant role in the pathogenesis of cardiovascular and metabolic diseases." (PMID 40717587, 2025). "Hence, FABP3 presents itself as a significant molecular target for regulating lipid metabolism and metabolic diseases." (PMID 38440405, 2024).
heart diseases (7 papers, 2014 to 2023). "As elevated FABP3 has been previously explored in the content of varied cardiac diseases, at least two mechanisms are involved in the regulation of FABP3 expression." (PMID 34458345, 2021). "In silico drug discovery was performed for a selected gene, FABP3, with the top-ranked compounds identified including protein inhibitors reportedly upregulated in heart disease." (PMID 25925353, 2015).